NADSYN1 (NAD synthetase 1)
Description:
Catalyzes the final step of the nicotinamide adenine dinucleotide (NAD) de novo synthesis pathway, the ATP-dependent amidation of deamido-NAD using L-glutamine as a nitrogen source.
Synonyms: FLJ10631; VCRL3
Tractability: Small molecule: a structure with a bound ligand is known. PROTAC: ubiquitination databases record sites on it; its protein half-life has been measured.
Gene: Protein-coding gene on chromosome 11 (71,453,109 to 71,524,107, forward strand). Ensembl gene ENSG00000172890.
Subcellular location (Human Protein Atlas): Vesicles; Cytosol; Golgi apparatus
Pathways (Reactome):
Metabolism: Nicotinate metabolism
Gene Ontology:
Molecular function: NAD+ synthase (glutamine-hydrolyzing) activity; protein binding; glutaminase activity; ATP binding
Biological process: 'de novo' NAD+ biosynthetic process from L-tryptophan; NAD+ biosynthetic process; NAD+ biosynthetic process via the salvage pathway
Cellular component: cytoplasm; cytosol
Genetic constraint (gnomAD): Loss-of-function variants: 80 observed, 95.41 expected, observed/expected ratio (o/e) 0.84, 90% interval 0.7 to 1.01. The upper end of that interval is the gene's LOEUF score, 1.01, which puts it in group 4 of 6, group 1 being the genes least tolerant of losing a copy. Missense variants: 828 observed, 926.24 expected, observed/expected ratio (o/e) 0.89, 90% interval 0.84 to 0.95. Synonymous variants: 366 observed, 359.4 expected, observed/expected ratio (o/e) 1.02, 90% interval 0.93 to 1.11.
Homologues: Orthologues: chimpanzee NADSYN1 (98% identical), guinea pig NADSYN1 (88% identical), pig NADSYN1 (88% identical), rat Nadsyn1 (86% identical), mouse Nadsyn1 (85% identical), macaque NADSYN1 (61% identical), Drosophila melanogaster Nadsyn (59% identical), zebrafish nadsyn1 (58% identical), Caenorhabditis elegans qns-1 (46% identical).
Diseases named in the same sentence as NADSYN1 in open-access papers:
NADSYN1 is named in the same sentence as 41 diseases in open-access papers, as found by Europe PMC text mining. Sharing a sentence is not in itself a finding about the gene and the disease. The quoted sentences say what the papers report.
vitamin D deficiency (5 papers, 2013 to 2023). A nutritional condition produced by a deficiency of VITAMIN D in the diet, insufficient production of vitamin D in the skin, inadequate absorption of vitamin D from the diet, or abnormal conversion of vitamin D to its bioactive metabolites. "The study of Xu X indicated that polymorphisms in CYP2R1-rs10766197 and DHCR7/NADSYN1-rs12785878 were associated with vitamin D deficiency in Uygur and Kazak ethnic populations, supporting a genetic effect on vitamin D status in minorities." (PMID 38124154, 2023). "Our study showed that the proportion of vitamin D deficiency was higher in the NH group than in controls, and rs12785878 (NADSYN1/DHCR7) and rs10877012 (CYP27B1) are correlated with NH risk and vitamin D deficiency." (PMID 37259065, 2023). "Third, this study is the first to analyze the effects of SNPs in the GC and NADSYN1 genes concomitantly on three cardio-metabolic risk factors (overweight, dyslipidemia, and vitamin D insufficiency/deficiency)." (PMID 24073860, 2013). "There were associations among NH, vitamin D deficiency and NADSYN1/DHCR7 and CYP27B1 polymorphisms, TT genotype of rs12785878 and GT genotype of rs10877012 could reduce the risk of vitamin D deficiency and NH." (PMID 37259065, 2023). "Findings from the present study suggested that NADSYN1/DHCR7 rs12785878 TT genotypes and CYP27B1 rs10877012 GT genotypes were associated with decreased risk of vitamin D deficiency." (PMID 37259065, 2023). "Recent genetic studies have associated vitamin D deficiency with several candidate genes including Cytochrome P450, family 2, R, (CYP2R1), the group-specific component gene (GC) and 7-dehydrocholesterol reductase/NAD synthetase 1 (DHCR7/NADSYN1)." (PMID 25405862, 2014).
breast carcinoma (3 papers, 2018 to 2022). "In the crude analysis, minor homozygotes of SNP proxy rs12791871 for GWAS SNP rs12785878 (located in NADSYN1 in chromosome 11) also had a statistically significant decreased risk of breast cancer (OR 0.73, 95% CI 0.55–0.95) compared with major homozygotes." (PMID 29291743, 2018). "Contradictory to this, SNPs whose minor alleles showed an association with an increased risk of low vitamin D—rs12791871, rs7944926 and rs3829251—of the NADSYN1 in chromosome 11 were, if anything, associated with a decreased risk of breast cancer." (PMID 29291743, 2018). "For example, higher VD levels were associated with lower methylation of Wnt Family Member 5A (WNT5A) and dickkopf 1 (DKK1) genes in colorectal cancer patients and higher methylation of Retinoid X Receptor Alpha (RXRA) and NAD Synthetase 1 (NADSYN1) genes in breast cancer patients." (PMID 36430854, 2022). "Changes in expression or methylation of GC, NADSYN1/DHCR7, and the other candidate genes may have less pervasive biological effects, but our findings support the hypothesis that these vitamin D-related genes and proteins may interact with circulating vitamin D levels to influence breast cancer risk." (PMID 29996894, 2018).
COVID-19 (3 papers, 2021 to 2022). A disease caused by infection with severe acute respiratory syndrome coronavirus 2. "COVID-19 patients were genotyped for variants in DHCR7/NADSYN1, GC, CYP2R1, VDR, PPCDC and DMGDH genes." (PMID 34150833, 2021). "The results here also highlighted the genetic contribution of specific haplotypes for VDR, DHCR7/NADSYN1, and GC genes to COVID-19 critical condition, emphasizing the importance of genotypic variations in determining disease severity in populations." (PMID 34835935, 2021). "Results of our study showed association of DHCR7/NADSYN1 rs12785878 and CYP2R1 rs10741657 variants with severe form of COVID-19 in adult patients." (PMID 34150833, 2021). "Our results pointed out to DHCR7/NADSYN1 rs12785878 and CYP2R1 rs10741657 variants, both involved in vitamin D synthesis, as potential risk factors of severe COVID-19." (PMID 34150833, 2021). "Specific SNPs located in the genes GC, DHCR7/NADSYN1, and VDR were associated with the critical COVID-19 condition among patients." (PMID 34835935, 2021). "Therefore, we evaluated genetic determinants of vitamin D (DHCR7/NADSYN1 rs12785878, GC rs2282679, CYP2R1 rs10741657, VDR rs2228570), zinc (PPCDC rs2120019) and selenium (DMGDH rs17823744) as risk factors for severe forms of COVID-19." (PMID 34150833, 2021). "Our study indicated an association between DHCR7/NADSYN1 rs12785878 and CYP2R1 rs10741657 variants and the severity of COVID-19, but the variants GC rs2282679 and VDR rs2228570 were not linked to a higher risk of severe COVID-19 in adults." (PMID 34150833, 2021).
type 1 diabetes (3 papers, 2012 to 2017). "For example, SNPs in NAD synthetase 1/ 7-dehydrocholesterol reductase (NADSYN1/DHCR7) gene locus and SNPs in CYP27B1, CYP2R1 genes and have been associated with type 1 diabetes or with type 1 diabetes related autoantibodies." (PMID 28976992, 2017).
autoimmune disease (2 papers, 2012 to 2020). A disorder resulting from loss of function or tissue destruction of an organ or multiple organs, arising from humoral or cellular immune responses of the individual to their own tissue constituents. "This set of SLE-associated genes includes DHCR7 and NADSYN1, enzymes involved in the biogenesis of vitamin D, a process known to play an important role in autoimmune disease susceptibility." (PMID 32620744, 2020).
melanoma (2 papers, 2016). A malignant, usually aggressive tumor composed of atypical, neoplastic melanocytes. "Another example is the genes related to melanoma, as they are also associated with skin color, eye color and albinism (SLC45A2), preterm birth (DHCR7), and Vitamin D levels (NADSYN1)." (PMID 27042214, 2016). "SNPs in NADSYN1 regulate serum vitamin D levels but are not related to esophageal or colon cancers or melanoma." (PMID 26959888, 2016).
acute coronary syndrome (1 paper, 2022). Signs and symptoms related to acute ischemia of the myocardium secondary to coronary artery disease. "The polymorphisms of DHCR7/NADSYN1 participate in susceptibility to many diseases, including deficiency of VitD, acute coronary syndrome, Alzheimer’s disease and ULs." (PMID 35795205, 2022).
deficient (1 paper, 2013). "In this study, the association of GC, CYP2R1, and DHCR7/NADSYN1 polymorphisms with vitamin D deficient rickets in Chinese subjects was reported for the first time." (PMID 24073854, 2013).
dermatitis (1 paper, 2024). An inflammatory process affecting the skin. "Both siblings, however, experienced previously unseen life-threatening episodes of pellagra-like dermatitis, a characteristic postnatal consequence of NAD deficiency that has not been reported previously in NADSYN1 deficiency." (PMID 38357931, 2024).
dyslipidemia (1 paper, 2013). "Our results obtained from non-diabetic Afro-Caribbean individuals confirm the associations of the GC and NADSYN1 genes with vitamin D status and suggest that polymorphisms in these genes contribute to dyslipidemia and overweight independently of 25 hydroxyvitamin D levels." (PMID 24073860, 2013). "The GC and NADSYN1 genes are associated with the vitamin D status and might contribute to dyslipidemia and overweight independently of 25(OH)D levels." (PMID 24073860, 2013). "Our aim was to assess the associations between vitamin D status, overweight, dyslipidemia and four SNPs of the GC, CYP27B1, and NADSYN1 genes in non-diabetic individuals with African ancestry." (PMID 24073860, 2013).
head and neck cancer (1 paper, 2024). A primary or metastatic malignant neoplasm affecting the head and neck. "Esophageal and head and neck cancers show the most striking NADSYN1 amplification frequency, (i.e., 19.23% and 13.77% of these tumors have amplified NADSYN1 gene expressions, respectively), implying that the PH pathway is heavily implicated in the pathophysiology of these two malignancies." (PMID 38396769, 2024).
multiple sclerosis (1 paper, 2022). A progressive autoimmune disorder affecting the central nervous system resulting in demyelination. "Although previous studies have found that NADSYN1 is closely associated with congenital diseases such as vertebral malformations, multiple organ defects, and multiple sclerosis." (PMID 36439178, 2022).
neuropathy (1 paper, 2024). A disorder affecting the nervous system that manifests with pain, tingling, numbness, and/or muscle weakness. "Specific genes increased in patients withoutlinezolid-associated neuropathy included ATG4C, BAX, and IGF1, while patients onlinezolid who suffered from neuropathy had an increase in AURKB, CASP3, CASP8, CDK1,CDKN1B, CEBPB, NADSYN1, NRF1, GPX7, and SBSN." (PMID 38939039, 2024).
Osteopenia (1 paper, 2018). Osteopenia is a term to define bone density that is not normal but also not as low as osteoporosis. "A statistically significant association was observed for the variants rs3794060 and rs4944957 of the DHCR7/NADSYN1 gene with osteopenia/osteoporosis." (PMID 30150596, 2018). "Moreover, an association was observed for the variants rs3794060 and rs4944957 of the DHCR7/NADSYN1 gene with osteopenia/osteoporosis." (PMID 30150596, 2018). "However, an association of the NADSYN1/DHCR7 gene with osteopenia/osteoporosis was identified." (PMID 30150596, 2018).
rickets (1 paper, 2013). Bone softening and weakening usually caused by deficiency or impaired metabolism of vitamin D. Deficiency of calcium, magnesium, or phosphorus may also cause rickets. "This study aimed to investigate the association between GC, CYP2R1, and DHCR7/NADSYN1 and rickets in northeastern Han Chinese children." (PMID 24073854, 2013). "However, our study found little evidence that DHCR7/NADSYN1 variants were associated with a genetic risk of rickets." (PMID 24073854, 2013).
Stroke (1 paper, 2020). Sudden impairment of blood flow to a part of the brain due to occlusion or rupture of an artery to the brain. "However, gene‐set rare‐variant association analyses showed significance difference in NADSYN1 gene between “Stroke” versus “Random” SCA." (PMID 32898326, 2020).
VATER syndrome (1 paper, 2023). "The clinical phenotype of NADSYN1-associated NAD deficiency is similar to that of the VATER syndrome." (PMID 37892645, 2023). "Our patient had a family history of abortions due to the VATER syndrome; however, genetic testing for NADSYN1 was not available." (PMID 37892645, 2023).
tumor (7 papers, 2022 to 2025). "By the disease groups, a higher scoring (strength of association) was noted for neoplasms, congenital diseases (mostly driven by the NADSYN1 gene), male and female urogenital diseases and nutritional/metabolic diseases." (PMID 36430729, 2022). "NMRK1 loss via either gene knock-out or knockdown decreased cellular NAD levels in FK866-treated, NAR-supplemented tumor cells, as did NADSYN1 knock-out." (PMID 38092728, 2023). "The authors speculated that in patients with B-ALL relapse, SIRT3 and NADSYN1 were up-regulated in response to certain tumor factors." (PMID 36439178, 2022). "Other genes were modulated in a different way in all three SCCs (NMNAT1, NMNAT2, NADSYN1, SIRT3, and CD38) or in two tumor types (NNMT, NMNAT3, ENPP2, PNP, and SIRT1)." (PMID 38254798, 2024). "Furthermore, a parallel study highlighted a Snai2-mediated transcriptional upregulation of NADSYN1, which binds PHB and amplifies tumor-promoting signaling." (PMID 41011271, 2025). "The authors speculated that it may be after a relapse of B-ALL, the up-regulation of three metabolic genes of NADSYN1, PARP6 and SIRT3, was promoted in response to certain tumor factors." (PMID 36439178, 2022). "Up to now, no data have been reported regarding NADSYN1 and tumor survival." (PMID 38254798, 2024).
metabolic disease (2 papers, 2022 to 2023). A congenital disorder (due to inherited enzyme abnormality) or acquired (due to failure of a metabolically important organ) disorder resulting from an abnormal metabolic process. "NADSYN1 deficiency is an inherited metabolic disorder that results in a deficiency of NAD+ during embryogenesis." (PMID 38132878, 2023).
NADSYN1 also shares sentences with these, for which no sentence is quoted: albinism (1 paper); Alzheimer disease (1); bladder cancer (1); cancer (1); chronic heart failure (1); colon cancers (1); colorectal cancer (1); female infertility (1); glaucoma (1); glioma (1); glomerulosclerosis (1); heart failure (1); leiomyoma (1); Obesity (1); osteoporosis (1); pancreatic tumor (1); pellagra- (1); prostate carcinoma (1); psoriasis (1); rheumatoid arthritis (1); tauopathy (1); Uterine leiomyoma (1).